KLHDC4 (kelch domain containing 4)
Synonyms: DKFZp434G0522
Tractability: PROTAC: ubiquitination databases record sites on it; its protein half-life has been measured.
Gene: Protein-coding gene on chromosome 16 (87,696,485 to 87,765,998, reverse strand). Ensembl gene ENSG00000104731.
Subcellular location (Human Protein Atlas): Nucleoli; Kinetochore
Gene Ontology:
Molecular function: protein binding
Genetic constraint (gnomAD): Loss-of-function variants: 78 observed, 54.03 expected, observed/expected ratio (o/e) 1.44, 90% interval 1.2 to 1.74. The synonymous counts are far from expectation, so gnomAD's model fits this gene poorly and the ratio says little. Missense variants: 944 observed, 663.32 expected, observed/expected ratio (o/e) 1.42, 90% interval 1.35 to 1.5. Synonymous variants: 372 observed, 269.75 expected, observed/expected ratio (o/e) 1.38, 90% interval 1.27 to 1.5.
Homologues: Orthologues: chimpanzee KLHDC4 (98% identical), macaque KLHDC4 (88% identical), pig KLHDC4 (82% identical), dog KLHDC4 (81% identical), rat Klhdc4 (81% identical), mouse Klhdc4 (80% identical), guinea pig KLHDC4 (80% identical), rabbit SLC7A5 (77% identical), tropical clawed frog klhdc4 (71% identical), zebrafish klhdc4 (70% identical), Drosophila melanogaster CG4069 (40% identical), Drosophila melanogaster slim (18% identical). Paralogues in human: HCFC1 (22% identical), LZTR1 (19% identical), KLHDC2 (17% identical), HCFC2 (17% identical), FBXO42 (16% identical), KLHDC1 (15% identical), RABEPK (15% identical), KLHDC10 (14% identical), KLHDC9 (14% identical), KLHDC3 (13% identical).
Diseases named in the same sentence as KLHDC4 in open-access papers:
KLHDC4 is named in the same sentence as 6 diseases in open-access papers, as found by Europe PMC text mining. Sharing a sentence is not in itself a finding about the gene and the disease. The quoted sentences say what the papers report.
nasopharyngeal carcinoma (5 papers, 2016 to 2025). A carcinoma arising from the nasopharyngeal epithelium. "In this study, we reported that KLHDC4, an uncharacterized kelch protein, is associated with nasopharyngeal carcinoma tumorigenesis and development." (PMID 27030985, 2016). "It was reported that the high expression of KLHDC4 is a poor prognostic factor in nasopharyngeal carcinoma." (PMID 38473243, 2024). "Similarly, KLHDC4 has been implicated in nasopharyngeal cancer by suppressing apoptosis, and CRISPR/Cas9 knockout of KLHDC4 has shown reduced tumour growth and migration, making it another potential therapeutic target, despite the lack of available inhibitors." (PMID 39887712, 2025). "KLHDC4 promotes NPC (Nasopharyngeal Carcinoma) oncogenesis by suppressing cellular apoptosis and may serve as a prognosis biomarker and a potential therapeutic target for NPC." (PMID 32851798, 2020). "We also examined KLHDC4 expression in 10 nasopharyngeal epithelial cell lines, including 3 immortalized normal nasopharyngeal epithelial lines (NP69, NPEC-N2-Bmi1 and NPEC-N5-Tert) and 7 nasopharyngeal cancer lines (CNE1, CNE2, SUNE1, SUNE2, HK1, HNE1 and HONE1)." (PMID 27030985, 2016).
breast carcinoma (2 papers, 2019 to 2025). "Similarly, KLHDC4’s association with the WNT pathway—implicated in breast cancer progression, immune modulation, invasion, and metastasis—highlights the complexity of DEG-driven mechanisms." (PMID 41020869, 2025).
Huntington disease (1 paper, 2024). Huntington disease (HD) is a rare neurodegenerative disorder of the central nervous system characterized by unwanted choreatic movements, behavioral and psychiatric disturbances and dementia. "KLHDC4 (cg08087060) is associated with Huntington’s disease, and CSMD1 (cg20912923) is related to learning and memory." (PMID 38663907, 2024).
tumor (3 papers, 2016 to 2025). "We next evaluated the in vivo effects of KLHDC4 deficiency on tumor growth by subcutaneous injection of parental or KLHDC4 KO CNE2 cells into nude mice and tumor growth were monitored." (PMID 27030985, 2016). "The positive rate of KLHDC4 in tumor tissues is 68.9% (51/84), and that in corresponding adjoining normal nasopharyngeal epithelia is 40.5% (30/84; χ2 = 12.027, P <0.001)." (PMID 27030985, 2016). "Furthermore, gene expression profiles from the GEO repository also reveal upregulation of KLHDC4 mRNA in tumor sections of different origins." (PMID 27030985, 2016). "Moreover, CRISPR/Cas9-mediated knockout of KLHDC4 in NPC cells results in a decrease in tumor cell growth and migration and is accompanied with increased apoptosis both in vitro and in vivo." (PMID 27030985, 2016). "Our data showed significant correlations of KLHDC4 expression levels with tumor staging." (PMID 27030985, 2016). "KLHDC4 favorites tumor development partly by inhibiting cellular apoptosis." (PMID 27030985, 2016). "Furthermore, elevated expression of cleaved caspase-3 and cleaved PARP were seen in tumor cells and xenografts after depletion of KLHDC4." (PMID 27030985, 2016). "Knockout (KO) of KLHDC4 via CRISPR/Cas9-mediated gene editing in NPC cell line dramatically inhibited cell proliferation, colony formation in soft agar and tumor formation in nude mice." (PMID 27030985, 2016). "In contrast to the parental CNE2 cells, which formed large tumors within 4 weeks (8 of 8 mice), mice injected with KLHDC4 KO cells displayed either no tumor formation or greatly retarded tumor growth (3 of 8 mice)." (PMID 27030985, 2016).
cancer (2 papers, 2016 to 2023). A tumor composed of atypical neoplastic, often pleomorphic cells that invade other tissues. "The KLHDC4 protein was detected in the cytoplasm of both normal nasopharyngeal epithelia and carcinoma cells." (PMID 27030985, 2016).
KLHDC4 also shares sentences with these, for which no sentence is quoted: cognitive abnormalities (1 paper).